ENSG00000252045
Gene: Small nucleolar RNA gene on chromosome 21 (32,538,299 to 32,538,434, forward strand). Ensembl gene ENSG00000252045.
Homologues: Orthologues: rat LOC120098367 (44% identical), rat Snora33 (43% identical), mouse Snora33 (41% identical), mouse Gm23722 (38% identical), mouse Gm55990 (31% identical). Paralogues in human: SNORA33 (46% identical).